PHGDH (phosphoglycerate dehydrogenase)
Diseases named in the same sentence as PHGDH in open-access papers (continued):
Sharing a sentence is not in itself a finding about the gene and the disease.
endometrial cancer (continued). "Among them, the expression level of PHGDH in tumor tissues was significantly higher than that in normal tissues, including endometrial cancer tissues (P < 0.001)." (PMID 36803157, 2023). "GO, KEGG pathway analysis, and GSEA were used to identify possible cellular mechanisms for the role of PHGDH in endometrial cancer." (PMID 36803157, 2023). "We then analyzed the relationship between PHGDH expression and clinical characteristics in 552 patients with endometrial cancer in the TCGA-UCEC dataset." (PMID 36803157, 2023). "The results showed that PHGDH expression was significantly higher in endometrial cancer tissues than in normal tissues at mRNA and protein levels." (PMID 36803157, 2023). "We then determined the correlation between PHGDH expression and clinical features in patients with endometrial cancer and used enrichment analysis bases to identify biological pathways associated with PHGDH." (PMID 36803157, 2023). "Our next studies will further focus on the specific targets of PHGDH’s role in endometrial cancer and its mechanisms." (PMID 36803157, 2023). "Then, the correlation between PHGDH expression and prognosis of endometrial cancer patients was analyzed." (PMID 36803157, 2023). "First, the expression of PHGDH in pan-cancer was investigated, as well as the expression and prognostic value of PHGDH in endometrial cancer." (PMID 36803157, 2023). "Next, to investigate the role of PHGDH in endometrial cancer progression, we explored the relationship between PHGDH expression and clinicopathological characteristics of endometrial cancer." (PMID 36803157, 2023). "Univariate logistic regression analysis showed the correlation between PHGDH expression and clinicopathological features of endometrial cancer." (PMID 36803157, 2023). "The prognostic value of PHGDH in endometrial cancer was presented using the Kaplan-Meier method." (PMID 36803157, 2023). "First, PHGDH mRNA expression was evaluated in pan-cancer, endometrial cancer, and benign tissues." (PMID 36803157, 2023). "However, how PHGDH affects the pathogenesis and prognosis of endometrial cancer remains to be further investigated." (PMID 36803157, 2023). "Our study provides new insights into the role of PHGDH in endometrial cancer progression." (PMID 36803157, 2023). "Our results suggest that PHGDH may be a promising biomarker for the diagnosis and prognosis of endometrial cancer." (PMID 36803157, 2023). "We found that PHGDH may be related to energy supply and glycolysis of endometrial cancer cells under hypoxic conditions." (PMID 36803157, 2023). "This suggests that PHGDH inhibitors may act as a new targeted agent to inhibit endometrial cancer growth." (PMID 36803157, 2023). "PHGDH has the potential to be a prognostic indicator for patients with endometrial cancer." (PMID 36803157, 2023). "PHGDH has also contributed to further our understanding of drug resistance in endometrial cancer." (PMID 36803157, 2023). "In addition, PHGDH expression was significantly upregulated in 23 cases of endometrial cancer tissues compared with paired paraneoplastic tissues (P < 0.01)." (PMID 36803157, 2023). "Moreover, multivariate regression analysis and visualized forest plots further confirmed that PHGDH expression was an independent prognostic factor for DFI in patients with endometrial carcinoma (HR = 1.614, 95% CI = 1.027–2.474, P = 0.038)." (PMID 36803157, 2023). "However, little is known about the clinical significance of PHGDH in endometrial cancer." (PMID 36803157, 2023). "Although the current study revealed a potential interaction between PHGDH and AMPK signaling pathway, further studies are needed to investigate how PHGDH precisely regulates the development of endometrial cancer." (PMID 36803157, 2023). "However, the influence of PHGDH on the progression of endometrial carcinoma remains unclear." (PMID 37387559, 2023).
endometrial cancer (continued). "Notably, we found that PHGDH is overexpressed in STIL and STIC lesions, which is consistent with its high expression in other cancer types, including breast, colon, and endometrial cancer." (PMID 37775701, 2023).
lymphoma (5 papers, 2022 to 2025). A malignant (clonal) proliferation of B- lymphocytes or T- lymphocytes which involves the lymph nodes, bone marrow and/or extranodal sites. "We reveal that upregulation of the SSP is a metabolic hallmark of B cell activation and lymphoma, with PHGDH being a critical player in humoral immunity and a clinically relevant target in lymphoma." (PMID 35316216, 2022). "Genetic loss and pharmacological inhibition of PHGDH reduces lymphoma progression in vivo." (PMID 35316216, 2022). "Human germinal center B cell‐derived lymphomas were found to overexpress high levels of the key SBP enzymes PHGDH and PSAT1." (PMID 38115544, 2024). "Taken together, this work provides important evidence that PHGDH is a viable target for the treatment of pathological B cell proliferation, either for the modulation of humoral immunity or in lymphoma." (PMID 35316216, 2022). "In contrast to healthy ABCs, where PHGDH blockade has a cytostatic effect, inhibition of this enzyme in lymphoma cells induces apoptosis, likely reflecting the impact of MYC overexpression." (PMID 35316216, 2022). "Taken together, these data provide evidence that PHGDH is an effective therapeutic target in MYC-driven lymphoma." (PMID 35316216, 2022). "As with the genetic KO, pharmacological inhibition of PHGDH with PH-755 also resulted in a significant reduction in lymphoma progression." (PMID 35316216, 2022). "Accordingly, PHGDH inactivation by the small molecule PH‐755 inhibited proliferation of Burkitt lymphoma cell lines in vitro and blocked disease development in a Eu‐Myc lymphoma mouse model." (PMID 38115544, 2024). "Inhibition of PHGDH induced apoptosis in lymphoma cells, reducing disease progression." (PMID 35316216, 2022). "This interaction between extracellular serine and PHGDH inhibition may open up new therapeutic opportunities, either in terms of combining pharmacological inhibition of PHGDH with a serine/glycine-free diet or in treating lymphoma in serine/glycine-depleted environments such as the CNS." (PMID 35316216, 2022). "Our observations support the hypothesis that it is serine and glycine themselves that are important for lymphoma cell proliferation and survival, as these cells retain the ability to cycle and have low rates of apoptosis when PHGDH is inhibited in serine/glycine-replete conditions." (PMID 35316216, 2022). "Importantly, inhibition of PHGDH, either specifically within lymphoma cells using an inducible KO transplantation model or globally using a pharmacological agent, reduces disease progression, highlighting this enzyme as a potentially novel therapeutic target in lymphoma." (PMID 35316216, 2022). "This raises the intriguing possibility that PHGDH inhibition could selectively target the humoral response with relative preservation of T cell responses, with important implications for the treatment of autoimmune disease and lymphoma." (PMID 35316216, 2022). "Immunoblotting and IHC showed higher expression of PHGDH and PSAT1 in B cells from lymphoma-bearing Eμ-Myc heterozygote mice when compared with WT C57BL/6J syngenic mice." (PMID 35316216, 2022). "In conclusion, these results show that inhibition of PHGDH in the absence of extracellular serine and glycine is able to inhibit purine synthesis and block entry into the S phase of the cell cycle and promote apoptosis of human lymphoma cell lines." (PMID 35316216, 2022).
metastatic disease (5 papers, 2017 to 2026). "For one MM patient (#1) at diagnosis, and for one patient (#4) with metastatic disease prior to therapy, PHGDH expression was negligible." (PMID 28855983, 2017).
Obesity (5 papers, 2021 to 2024). Accumulation of substantial excess body fat. "CpG sites in ABCG1 and PHGDH showed associations with metabolic measures, gene transcription, and metabolic measure ratios and were additionally linked to obesity or previous myocardial infarction, extending previously reported observations." (PMID 33413638, 2021). "In summary, these results indicate that myeloid PHGDH deficiency reverses diet-induced obesity." (PMID 38758794, 2024). "Consistently, immunohistochemical staining demonstrated decreased PHGDH expression in the kidneys of subjects with obesity or DKD." (PMID 35788583, 2022). "Consistently, phosphoglycerate dehydrogenase and serine levels are markedly downregulated in human subjects with diabetic kidney disease or obesity-related renal dysfunction." (PMID 35788583, 2022). "Deletion of PHGDH in adipocytes of mice with diet-induced obesity improves glucose tolerance." (PMID 35965483, 2022).
Sepsis (5 papers, 2017 to 2025). Sepsis is defined as life-threatening organ dysfunction caused by a dysregulated host response to infection. "Likewise, WAT epithelial, adipose stem and progenitor cells also exhibit increased activity in two further key metabolic reactions in serine metabolism, phosphoglycerate dehydrogenase (PGDH, EC 1.1.1.95, Cohen's d ≥0.4) and serine‐pyruvate aminotransferase (EC 2.6.1.51, Cohen's d ≥0.4) in sepsis." (PMID 40411399, 2025). "Furthermore, adeno-associated virus-mediated PHGDH overexpression in lung macrophages reduces sepsis-related inflammation and damage, highlighting PHGDH's nonmetabolic role in regulating macrophage-mediated inflammation and suggesting new therapeutic strategies for sepsis treatment." (PMID 40889684, 2025).
serine deficiency (5 papers, 2021 to 2025). "Several mutations of ETFDH and PHGDH genes have been associated with different forms of GA-II and serine deficiency, respectively." (PMID 34066864, 2021). "Here, the clinical and biochemical investigations indicate that ETFDH:p.Pro227Thr and PHGDH:p.Ser407Pro variants likely underlie the pathogenesis of GA-II and serine deficiency, respectively." (PMID 34066864, 2021). "Subsequently, we conducted the current study to investigate the effects of exogenous serine deficiency by using a serine-deficient diet or endogenous serine deficiency by supplementing an PHGDH inhibitor NCT-503, on hepatic fat accumulation in mice." (PMID 34712382, 2021). "Here, a well-established animal model of impaired serine biosynthesis induced by an inhibitor of PHGDH was used to observe the negative effects of serine deficiency on deiodinase expression in pregnant rats and development of their offspring." (PMID 36185664, 2022).
viral infection (5 papers, 2023 to 2025). "Four weeks after viral infection, immunofluorescence staining revealed that PHGDH was significantly overexpressed in the hippocampal region, with exclusive expression in astrocytes and negligible expression in neurons and microglia." (PMID 41344159, 2025). "We reveal that viral infection impairs serine metabolism by enhancing PHGDH deacetylation, which facilitates viral replication." (PMID 39207107, 2024). "Investigating gene polymorphisms and expression levels in large-scale populations enables the evaluation of the association between PHGDH, NLRP12, susceptibility to viral infections, disease severity, and treatment response." (PMID 38257759, 2023). "Viral infections are known to increase PHGDH and PSAT1 expression, but how they impact pulmonary functions remains unclear." (PMID 40262853, 2025). "We demonstrate that viral infection downregulates PHGDH expression and serine metabolism." (PMID 39207107, 2024). "We found that virus infection induced the localization of PHGDH to mitochondria." (PMID 39207107, 2024). "The interplay between PHGDH and viral infections has also been studied." (PMID 39207107, 2024). "A recent report has shown that PHGDH is downregulated during viral infections." (PMID 39207107, 2024). "Consequently, investigating the regulatory mechanisms of PHGDH during viral infection can shed light on its relationship with viral replication and immune response regulation and provide a deeper understanding of the pathogenesis of viral infections." (PMID 38257759, 2023). "However, the expression and function of PHGDH in viral infections remain unclear." (PMID 39207107, 2024). "Virus infection increased HDAC3 expression in PK-15 cells, which inversely correlated with KAT8 and mediated PHGDH deacetylation." (PMID 39207107, 2024). "In conclusion, PHGDH and NLRP12 play significant roles in virus-infection-related research." (PMID 38257759, 2023). "Furthermore, at the clinical population level, studying the significance and value of PHGDH and NLRP12 in viral infections becomes even more imperative." (PMID 38257759, 2023).
myocardial infarction (4 papers, 2021 to 2025). Gross necrosis of the myocardium, as a result of interruption of the blood supply to the area, as in coronary thrombosis. "Moreover, PHGDH significantly enhances cardiac repair and stimulates cardiomyocyte proliferation in adult mice following myocardial infarction." (PMID 40930719, 2025).
pulmonary fibrosis (4 papers, 2019 to 2024). Chronic progressive interstitial lung disorder characterized by the replacement of the lung tissue by connective tissue, leading to progressive dyspnea, respiratory failure, or right heart failure. "This region includes several potential candidate genes, particularly PHGDH (D-3-phosphoglycerate dehydrogenase), an oxidoreductase that has been associated previously with pulmonary fibrosis." (PMID 31636655, 2019). "Inhibition of the glycine synthesis enzyme phosphoglycerate dehydrogenase (PHGDH) attenuated features of pulmonary fibrosis, indicating the crucial role of this pathway in fibrogenesis." (PMID 34845494, 2022). "In addition, serine synthesis (including PHGDH expression) is increased in the lungs of patients with pulmonary fibrosis to promote collagen fiber synthesis." (PMID 38994199, 2024).
bone cancer (3 papers, 2021 to 2025). A primary or metastatic malignant neoplasm affecting the bone or articular cartilage. "Increased understanding of the role of metabolic pathways in the biology of primary bone cancers has led to the identification of potential therapeutic targets, such as 3-phosphoglycerate dehydrogenase (PHGDH), the rate-limiting enzyme in the biosynthesis of serine from glucose." (PMID 34319488, 2021).
cervical adenocarcinoma (3 papers, 2018 to 2021). An adenocarcinoma arising from the cervical epithelium. "PHGDH is elevated in cervical adenocarcinoma, and is associated with poorer prognosis." (PMID 33511334, 2020). "Another study revealed high PHGDH expression in cervical adenocarcinoma samples, and knockdown of PHGDH in a related xenograft model significantly inhibited cell proliferation and halted tumour progression in vivo." (PMID 29568346, 2018). "Previous study demonstrated that knockdown of PHGDH reduced Bcl‐2 expression in human cervical adenocarcinoma, but the interaction between PHGDH and Bcl‐2 remains unclear." (PMID 33732415, 2021). "PHGDH knockdown in cervical adenocarcinoma resulted in a decrease in Bcl2 expression, suggesting that baseline high PHGDH could also result in increased Bcl2, thereby mitigating the mitochondrial apoptotic response." (PMID 33511334, 2020).
embryonal carcinoma (3 papers, 2018 to 2021). A non-seminomatous malignant germ cell tumor characterized by the presence of large germ cells with abundant cytoplasm resembling epithelial cells, geographic necrosis, high mitotic activity, and pseudoglandular and pseudopapillary structures formation. "PHGDH inhibition promotes multi-lineage differentiation of embryonal carcinoma stem cells via ubiquitination and proteasomal degradation of Oct4 and positively regulating the stability of the differentiation marker β3-tubulin." (PMID 33801846, 2021). "Moreover, this study provided a link between embryonal carcinoma stem cell differentiation following PHGDH inhibition and the induction of Beclin-1 dependent autophagy and senescence of embryonal carcinoma stem cells." (PMID 33801846, 2021). "In line with this hypothesis, genetic PHGDH knockdown promoted mTOR-independent autophagy in embryonal carcinoma stem-like cells." (PMID 32138178, 2020). "Silencing of PHGDH leads to reduced expression of master transcriptional regulators of self-renewal and pluripotency, i.e., Oct4, Nanog, Sox2, and Bmi1, and diminishes the capacity of tumorsphere formation in embryonal carcinoma stem cells, breast CSCs, and patient-derived brain CSCs." (PMID 33801846, 2021).
endothelial dysfunction (3 papers, 2020 to 2025). In vascular diseases, endothelial dysfunction is a systemic pathological state of the endothelium (the inner lining of blood vessels) and can be broadly defined as an imbalance between vasodilating and vasoconstricting substances produced by (or acting on) the endothelium. "We found evidence supporting the causal relationship of epigenetic regulation of PHGDH in the kidney, potentially through endothelial dysfunction, inflammation, and atherosclerosis." (PMID 32917208, 2020). "For example, serine deprivation in the absence of a synthesizing enzyme phosphoglycerate dehydrogenase causes lethal vascular defects in mice, whereas serine-glycine metabolism is also required in angiogenesis and linked to endothelial dysfunction in response to oxidized phospholipids." (PMID 36454214, 2022). "These included genes such as CLNS1A, UGP2, RNF216, PHGDH, CKAP4, and IL6R, many of which are known to participate in inflammatory pathways, oxidative stress, and endothelial dysfunction." (PMID 41262879, 2025).
hyperhomocysteinemia (3 papers, 2021 to 2024). A serious metabolic condition caused by mutations in the MTHFR gene, medications, or nutritional deficiency. "Furthermore, hyperhomocysteinemia were found in offspring of pregnant rats administrated with PHGDH inhibitor." (PMID 36185664, 2022). "Also, offspring born to pregnant rats administered with a PHGDH inhibitor exhibited slower growth rates and hyperhomocysteinemia compared to offspring from mothers not administered with the inhibitor (P < 0.05)." (PMID 36185664, 2022).
lymph node metastasis (3 papers, 2014 to 2025). "Patients exhibiting high PSAT1 and SLC1A5 expression were more likely to develop lymph node metastasis, while high PHGDH, PSPH and SLC1A5 expression were associated with distant metastasis." (PMID 40660426, 2025). "PHGDH is a highly expressed oncogene in lung cancer due to the active serine synthesis in this disease, and its elevated expression is positively associated with lymph node metastasis in NSCLC55." (PMID 38945960, 2024). "Furthermore, elevated PHGDH levels correlated significantly with larger tumor size, lymph node metastasis, and more advanced TNM stage." (PMID 38945960, 2024). "PHGDH expression also demonstrated a positive correlation with the TNM (tumor status, lymph node metastasis, distant metastasis) stage, as revealed by immunohistochemical analysis." (PMID 38945960, 2024).
renal carcinoma (3 papers, 2013 to 2024). A carcinoma arising from the epithelium of the renal parenchyma or the renal pelvis. "In renal carcinoma, in which PHGDH represents the key regulator of the HIF-2α pathway, targeted inactivation of PHGDH may be promising for treating patients resistant to HIF-2α antagonists." (PMID 30857125, 2019).
thyroid cancer (3 papers, 2019 to 2024). "PHGDH regulates the stemness of cancer cells and induces thyroid cancer cell proliferation and tumorigenesis, and is also associated with thyroid cancer aggressiveness." (PMID 38945960, 2024). "In thyroid cancers, the expression of proteins related to serine metabolism, including PHGDH, is more prevalent in anaplastic thyroid cancer than in papillary thyroid cancer." (PMID 38945960, 2024). "Several studies have revealed the importance of the SSP in differentiated thyroid cancer using immunohistochemical analysis and the expression level of PHGDH, the rate-limiting enzyme in the SSP51,52." (PMID 38331894, 2024).